PAX3 (paired box 3)
Diseases named in the same sentence as PAX3 in open-access papers (continued):
Sharing a sentence is not in itself a finding about the gene and the disease.
melanoma (continued). "Additionally, we examined the immunohistochemical localization of PAX3 in healthy human corneal-conjunctival tissue sections as well as in conjunctival/limbal melanoma specimens." (PMID 40216818, 2025). "Further investigation into mechanisms by which PAX3 influences corneal pathophysiology and contributes to conjunctival/limbal melanoma pathogenesis could identify potential therapeutic targets for this aggressive ocular malignancy." (PMID 40216818, 2025). "Here, we revealed several previously unknown potential gene targets of PAX3 and provide some insight into the wide functions of PAX3 in the regulation of melanoma growth, migration, and survival." (PMID 40428399, 2025). "The role of PAX3 may differ depending on how melanoma is induced and promoted, such as genetic, environmental or other variables." (PMID 40428399, 2025). "In these cells, we identified several known melanoma PAX3 targets, including MITF and BRN2/POU3F2." (PMID 40428399, 2025). "The MC extract increased PAX3 expression, which had increased with melanoma cell treatment." (PMID 39684511, 2024). "PAX3 is another gene involved both in embryogenesis and melanoma." (PMID 38673496, 2024). "We investigated PAX3 expression in the lungs of mice injected with B16 mouse melanoma cells." (PMID 39684511, 2024). "In agreement, TBX2 expression followed closely that of PAX3 in human melanomas." (PMID 34819350, 2021). "PAX3 is also frequently expressed in primary melanoma and to a lesser extent in benign nevi." (PMID 34071193, 2021). "Intriguingly, while some NCSC factors, such as SOX10 and YY1, are activated upon melanoma formation and are required for melanoma growth, other NCSC-associated factors, such as CD271/NGFR/p75NTR, PAX3, and FOXD3 promote melanoma cell invasiveness and metastasis formation." (PMID 34417458, 2021). "The MET gene in melanoma is regulated by PAX3, SOX10 and MITF." (PMID 33807778, 2021). "Additionally, the expression levels of MART-1, MAGE-A3 and PAX3 on CTCs have prognostic significance in patients with melanoma, and these proteins are highly expressed in melanoma tissues." (PMID 31980023, 2020). "We could confirm the correlation of MITF with BRN2 and PAX3 expression at RNA level and at protein level in a panel of melanoma cell lines." (PMID 30277012, 2019). "By performing ChIP we could show that PAX3 bound the region covering the P2 site, further supporting that this site, which is also important for the regulation by BRAF is used by PAX3 in melanoma cells." (PMID 30277012, 2019). "However, we discovered a novel role for YAP in melanoma, where it acts as cofactor for PAX3-driven expression of MITF, thereby regulation not only proliferation but also differentiation." (PMID 29545604, 2018). "The specific role of PAX3 in the biology of melanoma CTCs requires further investigation." (PMID 28978038, 2017). "Interestingly, GILT expression inhibits a tumorigenic molecule, paired box-3 (PAX-3) protein, in melanoma via the autophagy pathway." (PMID 29399381, 2017). "Further study of the relationship between PAX3 expression in melanoma CTCs with early response to MAPK inhibitors, in a larger cohort of patients, may provide an insight into its role in the development of acquired resistance and its biomarker utility." (PMID 28978038, 2017). "It is possible that PAX3 might orchestrate melanoma metastasis by maintenance of the “stem cell” phenotype of these cells during migration." (PMID 28978038, 2017). "In melanoma, FOXD3 increases PAX3 expression and contributes to melanoma progression." (PMID 27926503, 2017). "Indeed, recent reports have suggested that melanoma cells switch back to the embryogenetic program initiated during neural crest formation by means of several factors as PAX3 and MITF." (PMID 29156734, 2017). "PAX3 is also highly expressed in primary and secondary melanoma tumours." (PMID 28978038, 2017).
melanoma (continued). "Since inhibition of GSK3β in melanoma cells leads to cellular changes paralleling PAX3 inhibition, it was claimed that GSK3β regulates proliferation and morphology of melanoma cells through phosphorylation of PAX3." (PMID 27906130, 2016). "We identified SKI as an MAPK-regulated suppressor of PAX3 in melanoma cells." (PMID 26977879, 2016). "Because we had identified the SMAD2/4/SKI complex as relevant for the inhibitory action of nelfinavir on PAX3 transcription, and nelfinavir counteracted the MAPKi-induced tolerance in melanoma cells, we wanted to identify the link between the SMAD/SKI suppressor complex and MAPK signaling." (PMID 26977879, 2016). "The previous studies have reported that PAX3 may play an oncogenic function in some cancers such as glioblastomas and melanomas, whereas our data suggest that PAX3 acts as an oncosuppressor in thyroid cancer." (PMID 27458157, 2016). "In addition, we have shown previously that reduced PAX3 expression sensitizes melanoma cells to MEK inhibitors." (PMID 26977879, 2016). "Our data showed that PAX3 re-expression increased phosphorylation of Akt and FOXO3a in U251 cells and phosphorylation of Erk in A375 cells, suggesting that PAX3 plays a tumor-promoting role in glioblastomas and melanomas probably through activating these signaling pathways." (PMID 27458157, 2016). "Given that oncogenic function of PAX3 has been previously reported in other cancers such as glioblastomas and melanomas, we attempted to determine the role of PAX3 in glioblastoma cell line U251 and melanoma cell line A375." (PMID 27458157, 2016). "To determine mechanisms behind this differential downstream target gene regulation, we performed immunoprecipitation to assess post-translational modifications of the PAX3 protein as well as RNAseq to determine PAX3 transcript expression profiles in melanocytes compared to melanoma cells." (PMID 25880082, 2015). "We next assessed whether the differences observed in transcript expression profiles could be due to differential post-translational modifications of the PAX3 protein in the melanocyte cultures relative to melanoma cell lines." (PMID 25880082, 2015). "If proven in a larger cohort, differences in PAX3 expression profiles may, in the future, be used to stratify melanoma tumours for diagnosis, prognosis and potential treatment." (PMID 25880082, 2015). "The difference in PAX3 transcript expression profiles could, if proven in a larger cohort of cell lines and melanoma tissue samples, provide a tool for stratification of melanomas for diagnosis and treatment." (PMID 25880082, 2015). "We have also identified PAX3 expression at all stages of melanoma progression." (PMID 25880082, 2015). "Additionally, there were differences in PAX3 transcript expression profiles between melanocytes and melanoma cells." (PMID 25880082, 2015). "We previously identified PAX3 downstream target genes in melanocytes and melanoma cells." (PMID 25880082, 2015). "Since this differential regulation of melanoma cells by PAX3 may play a role in melanomagenesis, we sought to investigate the possible mechanisms behind this differential target gene selection." (PMID 25880082, 2015). "Here we first confirmed the differential PAX3 mediated regulation of downstream target genes, and then compared the PAX3 transcript expression profiles and post-translational modifications of PAX3 in several melanoma cell lines compared to normal melanocytes in vitro." (PMID 25880082, 2015). "This suggests that PAX3 phosphorylation or ubiquitination are not the likely mechanisms causing differential downstream target gene regulation between melanocytes and melanoma cell lines." (PMID 25880082, 2015). "Conversely, overexpression of PAX3 rescued melanoma cells from TGF-β-induced cell cycle arrest." (PMID 24188742, 2014). "As in development, PAX3 plays an anti-apoptotic role in melanoma and RMS." (PMID 24188742, 2014).
melanoma (continued). "Four melanoma cell lines chosen from this panel were transfected with siRNAs against PAX3 to determine whether migration of the melanoma cells depended on PAX3 expression." (PMID 24062982, 2013). "Phosphorylated STAT3 transcriptionally activates PAX3 expression in melanocytes, and the silencing of STAT3 or PAX3 using RNAi was recently shown to inhibit the growth of melanoma cells, particularly in melanoma cells that have acquired resistance to the BRAF inhibitor, vemurafenib." (PMID 24062982, 2013). "Involvement of PAX3 in melanoma migration is further supported by evidence showing that other genes associated with cell migration, including MCAM, CSPG4, and CXCR4, are targeted by PAX3, as shown by ChIP assay in A2058 melanoma cells." (PMID 24069584, 2013). "Moreover, the morphological effects of knocking down PAX3 versus MITF in melanoma cells were found to differ." (PMID 24062982, 2013). "PAX3 has been shown to prevent apoptosis in melanoma cells via a range of mechanisms." (PMID 24069584, 2013). "The observed low frequency (∼20%) of incidental co-expression of PAX3 and Ki67 could simply reflect progressive deregulation of growth control in melanoma cells, as marked by Ki67 expression." (PMID 24062982, 2013). "In addition, we show that in melanoma cell lines with lower levels of MITF expression, knockdown of PAX3 expression inhibits melanoma cell migration, whereas in melanoma cell lines with higher levels of MITF, knockdown of MITF enhances cell migration." (PMID 24062982, 2013). "Importantly, the transfection of melanoma cells with antisense PAX3 oligonucleotides triggers cell death by inducing apoptosis, highlighting the potential therapeutic option of targeting PAX3 in melanoma patients." (PMID 21876729, 2011). "Interestingly, melanoma metastases show significantly less PAX3-positive than MITF-positive cells, and generally these were weakly stained for PAX3." (PMID 20421967, 2010). "We also show that PAX3- positive epidermal melanocytes of normal skin are molecularly distinct from those of the hair follicle, which like melanoma cells express Melanoma cell adhesion molecule (MCAM, also known as MUC18/CD146), associated with cell migration and melanoma progression and metastasis." (PMID 20421967, 2010). "Expression of the melanoma progression marker MCAM was also analysed relative to PAX3." (PMID 20421967, 2010). "It suggests that regulation of migration might be one of the roles of PAX3 in melanoma, as it is in development, where Pax3 regulates cMet." (PMID 20421967, 2010). "BCL2L1 expression in normal PAX3-positive melanocytes indicates that they might utilise the same cell survival regulatory mechanism as melanoma cells, in order to sustain continuous renewal in the ever-changing environment of the epidermis." (PMID 20421967, 2010). "PAX3 is previously reported as an antiapoptotic regulator in tumours, including melanoma." (PMID 20421967, 2010). "However, PAX3-positive cells of normal skin samples generally showed weaker staining and far fewer cells were positive, compared to those in naevi and primary melanoma samples." (PMID 20421967, 2010). "Here we confirm that PAX3 is present in the majority of naevus and melanoma cells." (PMID 20421967, 2010). "Fourth, amplification of chromosome 3p and hypo-methylation of PAX3 together may elevate MITF expression in melanoma, which may up-regulate the downstream targets of MITF." (PMID 20925909, 2010). "As expected PAX3 expression was observed in naevi and melanoma cells." (PMID 20421967, 2010). "Finally, the Pax3 transcription factor is expressed in both myogenic and melanoma cells and plays a key role in cell migration during embryonic development and specification of the muscle stem cell niche." (PMID 20174581, 2010).
melanoma (continued). "Further investigation into the mechanisms by which PAX3 contributes to conjunctival/limbal melanoma pathogenesis could lead to the identification of potential therapeutic targets and improve our understanding of this rare but one of the most aggressive ocular malignancies." (PMID 40216818, 2025). "However, since these datasets were derived from bulk tissue samples, the observed PAX3 upregulation could be attributed to either an increased number of melanocytes within the tumor or enhanced PAX3 expression within the melanoma cells themselves." (PMID 40216818, 2025). "Additionally, PAX3 expression was studied in conjunctival/limbal melanoma specimens." (PMID 40216818, 2025). "In melanomas, PAX3 is associated with non-chronic sun-damaged tumors and with tumors that are caused by chronic exposure to the sun, with the latter having the ability to affect molecules included in the PAX3 pathway and lead to its loss of function." (PMID 38673496, 2024). "Since in vivo tumors contain a mix of melanoma and nonmelanoma cells, we also asked whether any correlation with PAX3 or MITF was observed in 53 melanoma cell lines grouped according to four different melanoma phenotypes distinguished by SOX10, SOX9, and MITF expression." (PMID 34819350, 2021). "In addition, collagen stiffening can promote melanoma differentiation via YAP/paired box 3 (PAX3)-mediated MITF expression, supporting the notion that collagen density and rigidity may also govern melanoma cell plasticity and intra-tumor heterogeneity." (PMID 32466585, 2020). "Linked by a network of overlapping functions in melanoma progression, melanoma cell adhesion molecule (MCAM), galectin-3 (Gal-3), chondroitin sulfate proteoglycan 4 (CSPG4), matrix metalloproteinase 2 (MMP-2), and paired box 3 (PAX-3) potentially act as biomarkers and targets in melanoma metastasis." (PMID 33490091, 2020). "Furthermore, cancer progression may employ altered phosphorylation of pivotal transcription factors, as has been suggested for MITF, PAX3, and β-catenin in melanoma." (PMID 29315345, 2018). "However, the recently proposed theory that melanoma progression is driven by those melanoma cells showing a highly motile, less differentiated (stem-like) phenotype, and the crucial roles PAX3 plays in melanocyte development, implies that it is more than just a lineage marker." (PMID 24069584, 2013). "However, it has recently been suggested that melanoma may be driven by cells with a less differentiated, highly motile phenotype and that PAX-3 may actively drive melanoma progression." (PMID 24069584, 2013). "From these reviews and others we have identified five melanoma biomarkers consistently associated with melanoma progression – melanoma cell adhesion molecule (MCAM), galectin-3 (Gal-3), matrix metalloproteinase-2 (MMP-2), chondroitin sulfate proteoglycan 4 (CSPG4), and paired box 3 (PAX3)." (PMID 24069584, 2013). "Although PAX3 is recognised as a key embryonic regulator of melanocyte specification and development, its expression and function in differentiated epidermal melanocytes of adult human skin is largely unexplored and its role in melanoma remains unclear." (PMID 20421967, 2010). "Thus in addition to amplification of segment 9 CNV the hypo-methylation of PAX3 in melanoma may also up-regulate the melanoma-specific gene expressions." (PMID 20925909, 2010). "Therefore, inhibitors of PAX3/MITF expression may sensitize melanomas to BRAF/MEK inhibitors." (PMID 38473380, 2024). "In melanomas treated with BRAF and MEK inhibitors, PAX3 and MITF expression increases and appears to contribute to the early drug tolerance state." (PMID 38473380, 2024). "MC extract administration induced the amelioration of melanoma by controlling the PAX3/PTEM/PIP3/Akt/mTORC1 and PAX3/MITF/CDK2·c-Met·Bcl2·RAB27A signaling pathways, which are involved in melanoma proliferation and invasion." (PMID 39684511, 2024).
melanoma (continued). "More recent studies have examined the role of PAX3 in early drug tolerance to BRAF and MEK inhibitors in melanoma." (PMID 38473380, 2024). "PAX3, a transcription factor involved in melanocyte development, the receptor tyrosine kinase KIT, CDKN1C, and EPHA5 were upregulated in the melanoma compared to the atypical nevus, while NTRK3 and ROS1 were downregulated in the same comparison." (PMID 35052351, 2021). "MITF is known as a central regulator of melanoma cell survival, proliferation, and differentiation, and the factors that regulate it include MC1R, MART-1, SOX10 and PAX3." (PMID 33672928, 2021). "For instance, the transcription factors PAX3, FOXD3, and SOX10 are part of a gene regulatory network in early NC development that also supports melanoma cell growth, migration, and resistance to targeted therapy, respectively." (PMID 34417458, 2021). "Chromatin-immunoprecipitation (ChIP) for BRN2, performed on Dauv-1 melanoma cell extracts, followed by qPCR, revealed quantitative BRN2 binding to both binding sites, comparable to BRN2 binding on the PAX3 promoter." (PMID 34140478, 2021). "It is difficult to separate its function in melanoma plasticity entirely from its various upstream regulators including SOX10, PAX3, and FOXD3 among others, as they are tightly connected." (PMID 34071193, 2021). "In this context, PRMT5 control of SKI enhances melanoma growth by upregulating SOX10 and PAX3, which drive melanoma growth." (PMID 32743345, 2020). "Nelfinavir has been identified as a potent suppressor of PAX3 and MITF expression and sensitizer of BRAF and NRAS mutant melanoma cells to MAPK pathway inhibitors." (PMID 33322354, 2020). "Remarkably, proliferative melanoma samples express high levels of MITF (melanocyte inducing transcription factor), SOX10 (SRY-box 10) and PAX3 (paired box 3) genes." (PMID 31383874, 2019). "MITF is essential for melanoma cells and we discovered that BRAF employs a PAX3/BRN2 rheostat to regulate MITF expression." (PMID 30277012, 2019). "Reflecting their cancer specific relevance, expression of MITF, PAX3, and BRN2 is significantly enriched in melanoma cell lines as seen in a panel covering >20 general cancer types." (PMID 30277012, 2019). "We found that PAX3 and YAP interact in melanoma cells and that depletion of YAP using small interfering RNA (siRNAs) results in decreased MITF mRNA expression in cells cultured on >1 GPa collagen." (PMID 29545604, 2018). "The evidence that a vast majority of melanoma CTCs express “stem cell” markers such as ABCB5, shown by flow cytometry and PAX3, by gene expression, argues for inclusion of such markers to increase the CTC detection rate by immunocytochemistry." (PMID 28978038, 2017). "Firstly, our data indicate that MYSM1 participates in the regulation of genes involved in melanoma survival and proliferation, such as c-MET, via functional interaction with the sequence-specific TF PAX3." (PMID 28978033, 2017). "In addition, co-localization of MYSM1 and PAX3 could be detected in the nuclei of exponentially growing A375 melanoma cells by IF staining – underpinning that these two transcriptional regulators co-operate in gene regulation in melanoma." (PMID 28978033, 2017). "Transcripts of MLANA, TYR, MAGEA3, PAX3, and ABCB5 were successfully identified from a single melanoma cell, as reflected by the increase in reciprocal Ct values (1/Ct)." (PMID 28978038, 2017). "Nelfinavir efficiently suppressed PAX3 and MITF expression in a panel of BRAF mutant melanoma cells and reduced the GI50 for the MEK inhibitor selumetinib in drug-tolerant A375 melanoma cells (A375-T) by ∼60-fold, comparable with the GI50 in sensitive cells." (PMID 26977879, 2016). "We have assessed the expression of PAX3, MITF and BRN2 in two melanocyte cultures (NHEM-n and NHEM-a) and two melanoma cell lines (WM115 and M14) by RT-qPCR and western blot." (PMID 25880082, 2015).